DPAGT1 (dolichyl-phosphate N-acetylglucosaminephosphotransferase 1)
Description:
UDP-N-acetylglucosamine--dolichyl-phosphate N-acetylglucosaminephosphotransferase that operates in the biosynthetic pathway of dolichol-linked oligosaccharides, the glycan precursors employed in protein asparagine (N)-glycosylation. The assembly of dolichol-linked oligosaccharides begins on the cytosolic side of the endoplasmic reticulum membrane and finishes in its lumen. The sequential addition of sugars to dolichol pyrophosphate produces dolichol-linked oligosaccharides containing fourteen sugars, including two GlcNAcs, nine mannoses and three glucoses. Once assembled, the oligosaccharide is transferred from the lipid to nascent proteins by oligosaccharyltransferases. Catalyzes the initial step of dolichol-linked oligosaccharide biosynthesis, transferring GlcNAc-1-P from cytosolic UDP-GlcNAc onto the carrier lipid dolichyl phosphate (P-dolichol), yielding GlcNAc-P-P-dolichol embedded in the cytoplasmic leaflet of the endoplasmic reticulum membrane.
Synonyms: G1PT; GPT; DPAGT2; D11S366; DGPT; ALG7; CDG-Ij; CDG1J; CMS13; CMSTA2; DPAGT; UAGT; UGAT
Tractability: Small molecule: a structure with a bound ligand is known; a high-quality ligand is known. Antibody: UniProt predicts a signal peptide or a membrane-spanning region. PROTAC: ubiquitination databases record sites on it; its protein half-life has been measured; a small molecule that binds it is known.
Target class: Enzyme; Transferase
Gene: Protein-coding gene on chromosome 11 (119,096,025 to 119,108,331, reverse strand). Ensembl gene ENSG00000172269.
Subcellular location: Endoplasmic reticulum membrane
Pathways (Reactome):
Disease: Defective DPAGT1 causes CDG-1j, CMSTA2
Metabolism of proteins: Biosynthesis of the N-glycan precursor (dolichol lipid-linked oligosaccharide, LLO) and transfer to a nascent protein
Gene Ontology:
Molecular function: protein binding; UDP-N-acetylglucosamine-dolichyl-phosphate N-acetylglucosaminephosphotransferase activity; UDP-N-acetylglucosamine-lysosomal-enzyme N-acetylglucosaminephosphotransferase activity; identical protein binding; phosphotransferase activity, for other substituted phosphate groups
Biological process: dolichol-linked oligosaccharide biosynthetic process; protein N-linked glycosylation
Cellular component: intracellular membrane-bounded organelle; membrane; endoplasmic reticulum membrane; Golgi apparatus
Genetic constraint (gnomAD): Loss-of-function variants: 25 observed, 41.82 expected, observed/expected ratio (o/e) 0.6, 90% interval 0.44 to 0.83. The upper end of that interval is the gene's LOEUF score, 0.83, which puts it in group 3 of 6, group 1 being the genes least tolerant of losing a copy. Missense variants: 381 observed, 531.22 expected, observed/expected ratio (o/e) 0.72, 90% interval 0.66 to 0.78. Synonymous variants: 193 observed, 215.16 expected, observed/expected ratio (o/e) 0.9, 90% interval 0.8 to 1.01.
Gene-disease validity (ClinGen):
ClinGen rates the evidence that DPAGT1 causes each of these diseases.
DPAGT1-congenital disorder of glycosylation (autosomal recessive): Definitive. DPAGT1-CDG is a form of congenital disorders of N-linked glycosylation characterized by hypotonia, intractable seizures, developmental delay, microcephaly and severe fetal hypokinesia.
Homologues: Orthologues: chimpanzee DPAGT1 (99% identical), dog DPAGT1 (96% identical), guinea pig DPAGT1 (95% identical), pig DPAGT1 (95% identical), macaque DPAGT1 (94% identical), mouse Dpagt1 (94% identical), rabbit DPAGT1 (94% identical), rat Dpagt1 (94% identical), tropical clawed frog dpagt1 (76% identical), zebrafish dpagt1 (75% identical), Drosophila melanogaster Alg7 (54% identical), Caenorhabditis elegans algn-7 (48% identical).
Diseases named in the same sentence as DPAGT1 in open-access papers:
DPAGT1 is named in the same sentence as 60 diseases in open-access papers, as found by Europe PMC text mining. Sharing a sentence is not in itself a finding about the gene and the disease. The quoted sentences say what the papers report.
congenital myasthenic syndrome (8 papers, 2013 to 2024). Congenital myasthenic syndrome (CMS) is a group of genetic disorders of impaired neuromuscular transmission at the motor endplate characterized by fatigable muscle weakness. "Missense DPAGT1 variants cause congenital myasthenic syndrome and disorders of glycosylation." (PMID 30388443, 2018). "Mutations in DPAGT1 are a newly recognised cause of congenital myasthenic syndrome." (PMID 23591138, 2013). "In some cases, treatments such as acetylcholinesterase inhibitors may be considered, particularly in patients with pathogenic variants in congenital myasthenia genes (CHRNA1, CHRND, DPAGT1, and GFPT1)." (PMID 38982518, 2024). "ARMCX4 interacts with DPAGT1, which suggests that ARMCX4 inhibits congenital myasthenic syndrome (CMS), GD, male infertility, and neonatal maxillofacial deformities by interacting with DPAGT1." (PMID 34912852, 2021). "Pathogenic mutations in DPAGT1 are manifested as two possible phenotypes: congenital disorder of glycosylation DPAGT1-CDG (also known as CDG-Ij), and limb-girdle congenital myasthenic syndrome (CMS) with tubular aggregates." (PMID 28662078, 2017). "DPAGT1 defects manifest as two alternative phenotypes: congenital disorder of glycosylation DPAGT1-CDG (MIM: 608093; previously known as CDG-Ij), and limb-girdle congenital myasthenic syndrome (CMS) (MIM 614750) with tubular aggregates." (PMID 28662078, 2017).
oral cancer (6 papers, 2014 to 2023). "Collectively, these studies suggest that dysregulation of the DPAGT1/Wnt/E-cadherin network underlies the etiology and pathogenesis of oral cancer." (PMID 24742667, 2014). "Although it has been reported that DPAGT1 upregulation was associated with tumor aggressiveness in oral cancer and esophageal squamous cell carcinoma, it remains unclear whether and how DPAGT1 upregulation is involved in breast cancer progression." (PMID 37463446, 2023). "Additionally, other genes were associated with the risk of other diseases, such as NARS, which causes nonsyndromic hearing loss, Leigh syndrome and Alpers syndrome, and DPAGT1, which is involved in the pathogenesis of oral cancer." (PMID 26550991, 2015). "Consistent with these regulatory cues, transcriptional expression of DPAGT1 is inappropriately induced in oral carcinoma." (PMID 24742667, 2014). "Further, modification of receptor tyrosine kinases (RTKs) with N-glycans is known to control their surface presentation via the galectin lattice, and thus increased DPAGT1 expression likely contributes to abnormal activation of RTKs in oral cancer." (PMID 24742667, 2014). "Here, we review studies describing how dysregulation of the N-glycosylation-regulating gene, DPAGT1, drives oral cancer." (PMID 24742667, 2014). "Since upregulation of DPAGT1 expression in OSCC is associated with increased modification of glycoproteins with complex N-glycans, it is likely that in the absence of mutations these structures are responsible for the observed increased activities of EGFR and FGFR in oral cancer." (PMID 24742667, 2014).
congenital disorder of glycosylation (3 papers, 2017 to 2025). Congenital disorder of glycosylation (CDG) is a fast growing group of inborn errors of metabolism characterized by defective activity of enzymes that participate in glycosylation (modification of proteins and other macromolecules by adding and processing of oligosaccharide side chains). "Pathogenic variants in DPAGT1 and ALG2 can also cause congenital disorders of glycosylation (CDG type Ij), which are associated with developmental delay and intellectual disability." (PMID 40442802, 2025). "DPAGT1-CDG is a Congenital Disorder of Glycosylation (CDG) that lacks effective therapies." (PMID 39466823, 2024).
developmental delay (3 papers, 2013 to 2025). "Pathogenic variants of DPAGT1 and ALG2 were reported in congenital disorder of glycosylation Ij (CDG Ij) with infantile spasms, developmental delay, microcephaly, and finger malformations." (PMID 36835142, 2023).
breast carcinoma (2 papers, 2022 to 2023). "Taken together, these results suggest that the DPAGT1/ADAM10 axis is associated with poor prognosis of patients with HER2+ breast cancer." (PMID 37463446, 2023). "The clinical significance of DPAGT1 protein levels was further examined in 170 paraffin-embedded (FFPE) HER2+ breast cancer specimens." (PMID 37463446, 2023). "Taken together, these results indicated that DPAGT1 upregulation correlated with poor prognosis in patients with HER2+ breast cancer." (PMID 37463446, 2023). "IHC statistical analysis revealed that high expression of ADAM10 was positively associated with shorter RFS and OS, and that ADAM10 expression correlated positively with DPAGT1 level in the 170 HER2+ breast cancer specimens." (PMID 37463446, 2023). "Inhibition of DPAGT1 resensitizes trastuzumab-resistant HER2+ breast cancer." (PMID 37463446, 2023). "However, our IHC staining showed that DPAGT1 was also localized at the plasma membrane (PM) in HER2+ breast cancer tissues." (PMID 37463446, 2023). "Furthermore, upon trastuzumab treatment, the more DPAGT1 was expressed in HER2+ breast cancer cells, the more DPAGT1 protein would be retrogradely transported from the plasma membrane to the ER." (PMID 37463446, 2023). "Therefore, our results demonstrated that, in HER2+ breast cancer, trastuzumab treatment induced PM-to-ER retrograde transportation of DPAGT1, which protected ADAM10 from ERAD via N-glycosylation, consequently resulting in robust HER2 shedding, trastuzumab resistance, and poor clinical outcomes." (PMID 37463446, 2023). "Interestingly, immunofluorescence (IF) staining and PM extraction assays showed that HER2+ breast cancer cell lines SK-BR-3 and BT-474 displayed clear PM localization of DPAGT1; however, it was rarely detected at the PM of cell lines that are not HER2+, such as MDA-MB-231 or MCF-7." (PMID 37463446, 2023). "Importantly, high DPAGT1 expression was inversely associated with relapse-free survival (RFS) and overall survival (OS) in patients with HER2+ breast cancer and in patients with HER2+ breast cancer who received trastuzumab treatment." (PMID 37463446, 2023). "Overexpression of DPAGT1, but not the enzyme-dead mutant DPAGT1-N185A, dramatically increased the level of p95HER2 in HER2+ breast cancer cells and the HER2-ECD level in the conditional medium, which was abolished by DPAGT1 inhibition with tunicamycin (TM)." (PMID 37463446, 2023). "In this study, we found that upregulated DPAGT1 was correlated with poor therapeutic response to trastuzumab and worse outcome in patients with HER2+ breast cancer." (PMID 37463446, 2023). "Intriguingly, analysis of the TCGA data showed that DPAGT1 expression was increased in multiple types of HER2-overexpressing human cancer, including breast cancer, gastric cancer, colorectal cancer, and uterine corpus endometrioid carcinoma." (PMID 37463446, 2023).
breast tumors (2 papers, 2023 to 2024). "High expression of DPAGT1 in the primary HER2+ breast tumors was associated with poor prognosis in patients, indicating that DPAGT1 intrinsically contributed to trastuzumab resistance." (PMID 37463446, 2023). "IHC staining analysis revealed that the expression of DPAGT1 was markedly increased in the pretherapeutic HER2+ breast tumors from patients who had recurrence within 5 years after surgery compared with that of patients without tumor recurrence." (PMID 37463446, 2023). "Importantly, inhibition of DPAGT1 resensitized trastuzumab-resistant HER2+ breast tumors." (PMID 37463446, 2023). "Dolichyl-phosphate N-acetylglucosaminephosphotransferase 1 (DPAGT1) is a key component of the N-glycosylation process, and the inhibition of DPAGT1 by the glycosylation inhibitor tunicamycin has been shown to resensitize trastuzumab-resistant HER2+ breast tumors." (PMID 39769140, 2024).
Cognitive impairment (2 papers, 2019 to 2026). Abnormal cognition is characterized by deficits in thinking, reasoning, or remembering. "Mild to severe cognitive impairment has been reported in patients carrying mutations in the SLC5A7 gene, DPAGT1 gene, SNAP25 gene, COL13A1 gene, MYO9A gene, MUNC13–1 gene, and in SCN4A-related CMS." (PMID 30808424, 2019).
congenital disorder of glycosylation type 1J (2 papers, 2013 to 2022). "As well as causing CMS, certain mutations in DPAGT1 have been reported to cause congenital disorder of glycosylation type 1J (CDG type 1J)." (PMID 23591138, 2013). "Initially mutations in DPAGT1 have been associated with the onset of the severe multisystem disorder – congenital disorder of glycosylation type 1J." (PMID 23591138, 2013). "In human populations, DPAGT1 missense mutations are associated with limb girdle congenital myasthenic syndrome-13 (CMS13; OMIM 614750) and congenital disorders of glycosylation type Ij (CDG1J; OMIM 608093), both characterized by defects in cognitive and in motor abilities." (PMID 36233305, 2022).
esophageal cancer (2 papers, 2021). A primary or metastatic malignant neoplasm involving the esophagus. "In esophageal cancer, LINC00467 can promote esophageal cancer cell proliferation by adsorbing miR-485-5p and reducing the inhibitory effect on the miRNA target gene, DPAGT1." (PMID 34362879, 2021).
esophageal squamous cell carcinoma (2 papers, 2022 to 2023). Esophageal squamous cell carcinoma (ESCC) is a type of esophageal carcinoma (EC) that can affect any part of the esophagus, but is usually located in the upper or middle third. "In Esophageal squamous cell carcinoma (ESCC), LINC00467 acted as an oncogene in ESCC by enhancing cell proliferation and preventing cell apoptosis via miR‐485‐5p/DPAGT1 axis." (PMID 36203193, 2022).
hepatocellular carcinoma (2 papers, 2018 to 2025). A malignant tumor that arises from hepatocytes. "For example, Tu sensitized hepatocellular carcinoma to cisplatin-induced apoptosis and reversed drug resistance by regulating the DPAGT1/Akt/ABCG2 pathway." (PMID 30413206, 2018). "Firstly, we analyzed the relationship between RELA or DPAGT1 expression and the prognosis of HCC patients using The Cancer Genome Atlas Liver Hepatocellular Carcinoma (TCGA‐LIHC) database." (PMID 40919676, 2025).
Infertility (2 papers, 2020 to 2021). "Furthermore, conditional knockout of Dpagt1 in oocytes recapitulates the phenotypes observed in Dpagt1 mutant females, and causes complete infertility." (PMID 32714760, 2020). "Moreover, the infertility‐causing defect in D166G‐Dpagt1 mutant females appears most likely stemming from the oocyte since Dpagt1‐cKO in oocytes resulted in the similar, though more severe, phenotypes." (PMID 32714760, 2020).
tuberculosis (2 papers, 2018 to 2026). A chronic, recurrent infection caused by the bacterium Mycobacterium tuberculosis. "These analogues show nanomolar antimicrobial potency, ablated inhibition of DPAGT1, much reduced toxicity, allowed effective treatment of Mycobacterium tuberculosis (Mtb) in mammals, providing leads for tuberculosis (TB) antibiotic development." (PMID 30388443, 2018).
adenoma (1 paper, 2021). A neoplasm arising from the epithelium. "Additionally, when we compared proteomic profiling of adenomas, to the proteomic expression of colon biopsies, there were some moieties (ATP5J2, DPAGT1, PTPLB, HERC1, and COX6C) that were down-regulated in both." (PMID 33799486, 2021).
male infertility (1 paper, 2021). The inability of the male to effect fertilization of an ovum after a specified period of unprotected intercourse. "ARMCX4 interacts with DPAGT1, which suggests that ARMCX4 inhibits male infertility by interacting with DPAGT1." (PMID 34912852, 2021).
metabolic syndrome (1 paper, 2025). A cluster of metabolic risk factors for CARDIOVASCULAR DISEASES and TYPE 2 DIABETES MELLITUS. "Muraymycin A1 (MA1), a newly identified natural product inhibitor of DPAGT1, holds strong potential to improve human health and treat diseases associated with prolonged ER stress, including inflammation- and immune-related disorders, cardiovascular disease, metabolic syndromes, and cancer." (PMID 41157066, 2025).
oral squamous cell carcinoma (1 paper, 2016). "The observed dependence of AJ assembly on Wnt/β-catenin dysregulation is in accordance with the effect the overexpression of DPAGT1, increased N-glycosylation, and epithelial discohesion observed in MDCK cells and in oral squamous cell carcinoma." (PMID 27427963, 2016).
retinal degeneration (1 paper, 2022). Degeneration of the retina. "In this study, we primarily focus on the role of a dolichol phosphate N-acetylglucosamine-1-phosphotransferase (DPAGT1) variant in the pathological events leading to retinal degeneration, which has yet to be fully elucidated." (PMID 36233305, 2022). "In this study, we found that the Dpagt1tvrm76 model recapitulates the retinal degeneration found in some human patients and enables researchers to better probe the pathogenesis of degenerative changes in the retina caused by DPAGT1 mutations." (PMID 36233305, 2022). "The results presented here demonstrate that DPAGT1 mutations may exist which predominantly present at an early age as a non-syndromic retinal degeneration." (PMID 36233305, 2022). "Typically, patients harboring DPAGT1 variants present with limb-girdle weakness, and retinal degeneration is not noted." (PMID 36233305, 2022). "Intravitreal injection of tunicamycin causes retinal degeneration driven by opsin hypoglycosylation, yet DPAGT1 function in the neural retina has not been thoroughly investigated." (PMID 36233305, 2022).
retinal diseases (1 paper, 2022). "DPAGT1 should, therefore, be considered as a candidate gene for retinal diseases which map within its vicinity." (PMID 36233305, 2022).
retinitis pigmentosa (1 paper, 2022). Retinitis pigmentosa (RP) is an inherited retinal dystrophy leading to progressive loss of the photoreceptors and retinal pigment epithelium and resulting in blindness usually after several decades. "Our results suggest the possibility of DPAGT1 mutations in human patients that present primarily with retinitis pigmentosa, with little or no muscle disease." (PMID 36233305, 2022).